NBPF19 (NBPF member 19)
Gene: Protein-coding gene on chromosome 1 (149,475,045 to 149,556,361, forward strand). Ensembl gene ENSG00000271383.
Subcellular location: Cytoplasm
Subcellular location (Human Protein Atlas): Cytosol; Primary cilium; Cytokinetic bridge; End piece; Golgi apparatus; Microtubules; Mid piece; Principal piece; Vesicles
Gene Ontology:
Cellular component: cytoplasm
Genetic constraint (gnomAD): Loss-of-function variants: 8 observed, 10.29 expected, observed/expected ratio (o/e) 0.78, 90% interval 0.46 to 1.4. The synonymous counts are far from expectation, so gnomAD's model fits this gene poorly and the ratio says little. Missense variants: 307 observed, 172.5 expected, observed/expected ratio (o/e) 1.78, 90% interval 1.62 to 1.94. Synonymous variants: 112 observed, 67.61 expected, observed/expected ratio (o/e) 1.66, 90% interval 1.42 to 1.91.
Homologues: Paralogues in human: NBPF20 (98% identical), NBPF10 (90% identical), NBPF14 (69% identical), NBPF26 (29% identical), NBPF12 (23% identical), NBPF9 (21% identical), NBPF8 (17% identical), NBPF15 (17% identical), NBPF1 (15% identical), NBPF11 (14% identical), NBPF3 (12% identical), NBPF4 (8% identical), and 1 more.
Diseases named in the same sentence as NBPF19 in open-access papers:
NBPF19 is named in the same sentence as 3 diseases in open-access papers, as found by Europe PMC text mining. Sharing a sentence is not in itself a finding about the gene and the disease. The quoted sentences say what the papers report.
leukemia (1 paper, 2025). A malignant (clonal) hematologic disorder, involving hematopoietic stem cells and characterized by the presence of primitive or atypical myeloid or lymphoid cells in the bone marrow and the blood.
tumor (2 papers, 2020 to 2022). "Furthermore, there were six genes (EGR1, MUC20, MUC3A, NBPF19, NOL4L, and OR4L1) that were simultaneously mutated in the tumor tissues and junction tissues." (PMID 33133167, 2020).
NBPF19 also shares sentences with these, for which no sentence is quoted: cancer (1 paper).